BACH2 (BACH transcriptional regulator 2)
Description:
Transcriptional regulator that acts as a repressor or activator (By similarity). Binds to Maf recognition elements (MARE) (By similarity). Plays an important role in coordinating transcription activation and repression by MAFK (By similarity). Induces apoptosis in response to oxidative stress through repression of the antiapoptotic factor HMOX1. Positively regulates the nuclear import of actin (By similarity). Is a key regulator of adaptive immunity, crucial for the maintenance of regulatory T-cell function and B-cell maturation.
Synonyms: BTBD25; IMD60
Tractability: Small molecule: it has a binding pocket of medium quality. PROTAC: UniProt records ubiquitination sites on it; ubiquitination databases record sites on it; its protein half-life has been measured.
Target class: Transcription factor
Gene: Protein-coding gene on chromosome 6 (89,926,528 to 90,296,923, reverse strand). Ensembl gene ENSG00000112182.
Subcellular location: Cytoplasm; Nucleus
Subcellular location (Human Protein Atlas): Nucleoplasm; Cytosol
Gene Ontology:
Molecular function: protein binding; sequence-specific double-stranded DNA binding; DNA-binding transcription factor activity, RNA polymerase II-specific; RNA polymerase II cis-regulatory region sequence-specific DNA binding; DNA binding; DNA-binding transcription factor activity; DNA-binding transcription repressor activity, RNA polymerase II-specific
Biological process: primary adaptive immune response involving T cells and B cells; negative regulation of transcription by RNA polymerase II; regulation of transcription by RNA polymerase II; regulation of DNA-templated transcription
Cellular component: cytoplasm; cytosol; nucleoplasm; nucleus; RNA polymerase II transcription regulator complex; chromatin
Genetic constraint (gnomAD): Loss-of-function variants: 5 observed, 64.09 expected, observed/expected ratio (o/e) 0.078, 90% interval 0.04 to 0.16. The upper end of that interval is the gene's LOEUF score, 0.16, which puts it in group 1 of 6, group 1 being the genes least tolerant of losing a copy. Missense variants: 824 observed, 1,143 expected, observed/expected ratio (o/e) 0.72, 90% interval 0.68 to 0.76. Synonymous variants: 446 observed, 460.82 expected, observed/expected ratio (o/e) 0.97, 90% interval 0.89 to 1.05.
Gene-disease validity (ClinGen):
ClinGen rates the evidence that BACH2 causes each of these diseases.
immunodeficiency 60 (autosomal dominant): Moderate.
Homologues: Orthologues: chimpanzee BACH2 (99% identical), macaque BACH2 (99% identical), dog BACH2 (94% identical), pig BACH2 (93% identical), guinea pig BACH2 (93% identical), mouse Bach2 (90% identical), rat Bach2 (90% identical), rabbit BACH2 (83% identical), tropical clawed frog bach2 (72% identical), zebrafish bach2b (58% identical). Paralogues in human: BACH1 (32% identical), KLHL12 (12% identical), KLHL29 (12% identical), KLHL2 (12% identical), KLHL22 (12% identical), KLHL3 (12% identical), KLHL4 (12% identical), KLHL17 (11% identical), KLHL31 (11% identical), KLHL32 (11% identical), KLHL21 (11% identical), IPP (11% identical), and 42 more.
Diseases named in the same sentence as BACH2 in open-access papers:
BACH2 is named in the same sentence as 132 diseases in open-access papers, as found by Europe PMC text mining. Sharing a sentence is not in itself a finding about the gene and the disease. The quoted sentences say what the papers report.
autoimmune disease (35 papers, 2014 to 2025). A disorder resulting from loss of function or tissue destruction of an organ or multiple organs, arising from humoral or cellular immune responses of the individual to their own tissue constituents. "BACH2 (located on chromosome 6q15) has been implicated in the pathogenesis of several autoimmune diseases, and its expression has been identified in B and T cells." (PMID 41462398, 2025). "BACH2 haploinsufficiency can lead to a syndrome of BACH2-associated immunodeficiency and autoimmune disorders." (PMID 41169388, 2025). "Additional studies in other autoimmune disorders have confirmed association of the same BACH2 alleles with Addison’s disease, type 1 diabetes, coeliac disease, and rheumatoid arthritis." (PMID 38108994, 2024). "Overall, mutation in the BACH2 gene can disrupt immune regulation, Treg function, B-cell differentiation, and antioxidant responses, increasing susceptibility to autoimmune diseases." (PMID 38891024, 2024). "Dysfunction of BACH2 is common in lymphomas, whereas BACH2 mutations are associated with autoimmune disease, akin to those in immune checkpoint genes, and cause Mendelian monogenic primary immunodeficiency." (PMID 35459932, 2022). "IKZF3 (Aiolos) and IKZF2 (Helios), and BACH2 have been implicated in other autoimmune disease such as systemic lupus erythematosus (SLE) and Rheumatoid Arthritis (RA)." (PMID 36284352, 2022). "The PTPN22, CTLA4, and BACH2 loci are well-known drivers of autoimmune disease and we identified the variants and haplotype blocks that have previously been described in AAD and common autoimmune comorbidities." (PMID 33574239, 2021). "BACH2 polymorphisms are associated with autoimmune disorders, including Addison’s disease (AD), Graves’ disease (GD), and probably type 1 diabetes (T1D)." (PMID 33966174, 2021). "The transcription factor Bach2 is a susceptible gene for numerous autoimmune diseases including systemic lupus erythematosus (SLE)." (PMID 31552021, 2019). "Of interest, variants at the BACH2 locus have been associated with multiple autoimmune diseases, including RA." (PMID 26776603, 2016). "Functional studies are now required to investigate the precise mechanisms by which variants in the BACH2 gene confer susceptibility to autoimmune disease." (PMID 27680876, 2016). "The exact mechanism by which BACH2 variants influence autoimmune disease risk requires further research, and a systematic analysis of variation in the region is now required in large cohorts of patients." (PMID 27680876, 2016). "The BACH2 locus has been implicated in the susceptibility to several autoimmune diseases, including celiac disease, type 1 diabetes, vitiligo, Crohn's disease, and multiple sclerosis." (PMID 24586183, 2014). "Associations with autoimmune diseases have been reported with BACH2." (PMID 38891024, 2024). "Currently, Bach2 SNPs are associated with autoimmune diseases." (PMID 37228820, 2023). "Furthermore, IKZF3 (Aiolos) and IKZF2 (Helios), and BACH2 have been implicated in other autoimmune diseases such as systemic lupus erythematosus (SLE) and Rheumatoid Arthritis (RA)." (PMID 36284352, 2022). "In addition to loci implicated in lymphocyte function and development shared with other autoimmune diseases such as HLA, BACH2, PTPN22 and CTLA4, we associate two protein-coding alterations in Autoimmune Regulator (AIRE) with AAD." (PMID 33574239, 2021). "In addition to the association with T1DM, other GWAS studies combined with meta-analyses have indicated that BACH2 SNPs are associated with other autoimmune diseases such as asthma, Cohn’s diseases, coeliac disease, vitiligo, and Grave’s disease." (PMID 32236312, 2020). "BACH2 is a transcriptional repressor crucial for the terminal differentiation and maturation of both T and B lymphocytes, and its loss is associated with severe autoimmune diseases." (PMID 32132179, 2020).
autoimmune disease (continued). "Our genetics study in mice suggests that humans carrying the genetic variations in the BACH2 gene may develop autoimmune diseases by inducing excessive pathogenic Tfh cells." (PMID 31552021, 2019). "Bach2 regulates antibody class switch in B cells, thus contributing to acquired immunity because it is identified as a susceptible gene in GWAS of various autoimmune diseases." (PMID 29636091, 2018). "The Treg-modulating factor BACH2 is indispensable for the inhibition of lethal inflammation, and a correlation between BACH2 and FoxP3 levels was identified in multiple sclerosis and Hashimoto’s thyroiditis, both autoimmune diseases." (PMID 41462398, 2025). "ROCK1 can indeed phosphorylate BACH2 in its heme-binding domain and prevent the heme-driven degradation of BACH2, thus helping protect BACH2 in settings marked by increased hemolysis, such as malaria and some autoimmune diseases." (PMID 39903532, 2025). "BACH2 (located on chromosome 6q15) is a gene recently studied in the pathogenesis of several autoimmune diseases." (PMID 36578493, 2022). "The search for variants of BACH2 could be a part of the early diagnosis panel that identifies individuals prone to develope a polyglandular autoimmunity, including those already diagnosed with an autoimmune disorder or in first-degree relatives of patients with APS." (PMID 36578493, 2022). "Variations within three of these genes (JAK2, BACH2, and NCF1) previously have been associated with autoimmune diseases." (PMID 33903979, 2021). "The BACH2 gene regulates B cell differentiation and function and is therefore biologically relevant for autoimmune disease pathogenesis." (PMID 34834585, 2021). "We identified genetic variations in JAK2, BACH2, and NCF1 that have been associated with autoimmune diseases such as inflammatory bowel disease and chronic granulomatous disease." (PMID 33903979, 2021). "BACH2 SNPs are associated with T1DM and other autoimmune diseases since this gene regulates T and B cell differentiation; therefore modulating autoimmune diseases by regulating the equilibrium between tolerance and immunity." (PMID 32236312, 2020). "Bach2, a protein that regulates gene expression, is required in the B cells and T cells of the immune system to protect against autoimmune disease." (PMID 31819031, 2019). "In murine models, disruption of the BACH2 gene results in mice that are phenotypically normal at birth, but which develop fatal autoimmune disease in the first months of life." (PMID 27680876, 2016). "Studies have suggested that dysregulation of BACH2 may contribute to immune dysfunction and the development of autoimmune diseases, including MS." (PMID 38891024, 2024). "Furthermore, some of these genes have been associated with susceptibility to the development of autoimmune diseases—JAK2, BACH2, and NCF1." (PMID 39598118, 2024). "BACH2 dysregulation may also confer disease vulnerability, including autoimmune diseases, by inducing IRF4 protein accumulation as well as the chromatin dissociation of PU.1 in B cells." (PMID 38605225, 2024). "GWAS revealed several susceptibility loci shared with other autoimmune disorders, such as the LIM domain containing preferred translocation partner in lipoma (LPP), BTB domain and CNC homolog 2 (BACH2), and MAGI3, which is associated with the progression to hypothyroidism." (PMID 36902117, 2023). "Given the critical role of Bach2 in both Th2 type inflammation and autoimmunity, Bach2 may function differentially in Th2 type inflammation within an autoimmune disease." (PMID 35313725, 2022). "While implicated variants were largely trait-specific, 40% of target genes of these variants (2,207 of 5,488) were implicated across more than one autoimmune disorder, with 11 genes implicated across a maximum of 9 traits (e.g., TYK2, ICAM1, ICAM3, TNFIP3, CLEC16A, BACH2)." (PMID 41361473, 2025). "How BACH2 variants influence autoimmune disease susceptibility is not yet understood." (PMID 27680876, 2016).
autoimmune disease (continued). "To determine the influence of the Bach2 gene knockout on pancreatic histology, we examined mice aged 8 and 18 weeks, the latter with and without HFD, and animals that had been treated for 6 weeks with poly I:C as a potential trigger of an autoimmune disease." (PMID 41169388, 2025). "In contrast, the Bach2 mice used in this study had a C57BL/6N background, which does not predispose them to autoimmune diseases at young age." (PMID 41169388, 2025).
Autoimmunity (26 papers, 2011 to 2025). The occurrence of an immune reaction against the organism's own cells or tissues. "Overall, these data reveal a potential mechanism by which genetic predisposition shapes T cell function in autoimmunity and identify miRNAs and BACH2 as potentially druggable targets for the treatment of PSC." (PMID 38901430, 2024). "BACH2 haploinsufficiency can lead to a syndrome of BACH2-associated immunodeficiency and autoimmunity." (PMID 39595046, 2024). "Understanding the mechanisms by which BACH2 mutations contribute to autoimmunity is essential for developing targeted therapies for these conditions." (PMID 38891024, 2024). "Intriguingly, the transfer of BACH2-deficient TREG into recipient mice was shown to induce signs of autoimmunity." (PMID 38901430, 2024). "Recent human genetic studies indicated a genetic polymorphism within the BACH2 gene locus and its association with autoimmune conditions such as autoimmune thyroid disease, Addison’s disease, systemic lupus erythematosus among others and diabetes type 1." (PMID 37160609, 2023). "Two missense heterozygous BACH2 variants previously reported in the literature were associated with autoimmunity as well as a CVID-like picture." (PMID 35313976, 2022). "Polymorphisms within the BACH2 locus were found to be associated with several autoimmune conditions, comprising vitiligo, rheumatoid arthritis, and systemic lupus erythematosus." (PMID 33966174, 2021). "Our findings identify Bach2 as a crucial negative regulator of Tfh cells at steady state and prove that Bach2 controls autoimmunity in part by restraining accumulation of pathogenic Tfh cells." (PMID 31552021, 2019). "Given its association with multiple autoimmune conditions, BACH2 can be considered a “universal” autoimmune susceptibility locus." (PMID 27680876, 2016). "The BACH2 protein plays a crucial role in T lymphocyte maturation, and allelic variation in its gene has been associated with a number of autoimmune conditions." (PMID 27680876, 2016). "Further, BACH2 deficiency or mutation results in severe autoimmunity." (PMID 38891024, 2024). "Recently, a case of early-onset SLE in a BRIDA (BACH2-related immunodeficiency and autoimmunity) patient has suggested that BACH2 variants may constitute a potential monogenic cause of SLE." (PMID 38420886, 2024). "By analogy, it seemed plausible that BACH2 gene polymorphism, implicated in lymphocyte differentiation and function, might equally promote multitarget autoimmunity." (PMID 33966174, 2021). "We found that induced immunity and autoimmunity are differentially affected by Bach2 deficiency." (PMID 31819031, 2019). "In humans, a number of common variants in linkage disequilibrium (LD) at the BACH2 locus have been consistently associated with autoimmune conditions, including type 1 diabetes, celiac disease, autoimmune thyroid disease, Crohn's disease, multiple sclerosis, vitiligo, and rheumatoid arthritis." (PMID 27680876, 2016). "Additionally, a report linked a BACH2 polymorphism with polyglandular autoimmunity." (PMID 38891024, 2024). "Since cisplatin is mainly excreted through the kidneys, variants in BACH2 might play a role in the pathogenesis of cisplatin-induced nephrotoxicity, though through which mechanism (cell proliferation, DNA damage, or autoimmunity) is unclear and warrants further investigation." (PMID 34834585, 2021). "To determine whether the lupus-inducing autoimmunity in Bach2-deficient mice was simply due to this Treg cell deficiency, we adoptively transferred normal Treg cells into Bach2 KO mice and were able to partially but significantly restore their Treg cell population." (PMID 31819031, 2019). "A syndrome of BACH2-related immunodeficiency and autoimmunity (BRIDA) that results from BACH2 haploinsufficiency has been reported, pointing to the clinical relevance of BACH2-mediated gene regulation." (PMID 39758820, 2025).
Autoimmunity (continued). "Previous homozygous mouse models have made substantial contributions to understanding the role of Bach2 gene in controlling autoimmunity, pulmonary alveolar proteinosis, and tumor immunosuppression." (PMID 37160609, 2023). "This is possible because Bach2 regulates cells involved in both Th2 immune responses and autoimmunity, such as B cells, Tfh cells, and Treg cells, even though the activities of these cells are distinct." (PMID 35313725, 2022). "Further investigations will help to understand the complex role of Bach2 in Th2 type inflammation and autoimmunity." (PMID 35313725, 2022). "Recent reports support the considerable role of the BACH2 gene in immune function and single organ autoimmunity." (PMID 33966174, 2021). "Bach2 also appears to regulate differentiation and effector functions of other T cell subsets including Treg and Th17 cells, which play prominent roles in autoimmunity when deregulated." (PMID 33093630, 2020). "We also provide the evidence that Bach2 controls autoimmunity in part by restraining aberrant Tfh cell formation." (PMID 31552021, 2019). "Bach2−/− mice developed autoantibodies and spontaneous lethal inflammatory diseases, suggesting an essential role of Bach2 in controlling autoimmunity." (PMID 31552021, 2019). "Variants in the BACH2 gene have yet to be studied in autoimmune Addison's disease (AAD), which is a rare but highly heritable, organ-specific autoimmune condition with a prevalence in the European Caucasian population of 110–220 cases per million." (PMID 27680876, 2016). "BACH2 prevents lethal autoimmunity through its role in Treg cell formation." (PMID 40270514, 2025). "appears to show that BTB domain and CNC homolog 2 (BACH2) gene polymorphism, implicated in lymphocyte differentiation and function, may also promote multitarget autoimmunity." (PMID 37937054, 2023). "Similarly, T-cell-specific Bach2 KO mice also develop autoantibodies, suggesting the coexistence of Th2-type inflammation and autoimmunity." (PMID 35313725, 2022). "BACH2-deficient mice have also been shown to have absent Treg cells and an excess of effector and memory T cells resulting in autoimmunity." (PMID 35313976, 2022). "However, the exact cellular and molecular mechanisms via which Bach2 protects the hosts from developing autoimmunity remains incompletely understood." (PMID 31552021, 2019). "Bach2−/− mice have been known to develop autoantibodies and age-related lethal autoimmunity." (PMID 31552021, 2019). "Thus, BACH2 plays a central role in restraining autoimmunity." (PMID 38891024, 2024). "Given the different molecular requirements for autoimmunity versus active immunization, it was possible that Bach2 deficiency might not affect Ab responses against self-antigens in the same was as those against exogenous antigens." (PMID 31819031, 2019). "The finding of association of a BACH2 variant with a further autoimmune condition, AAD, supports the hypothesis that variation in BACH2 may be a permissive immune system factor that is implicated in many or most organ-specific autoimmune conditions." (PMID 27680876, 2016). "The exact molecular mechanisms by which BACH2 protects hosts from the development of autoimmunity are not completely yet understood." (PMID 36578493, 2022). "In this study, we report that genetic deletion of Bach2 in T cells, but not in B cells, recapitulated the lupus-like autoimmunity in Bach2−/− mice." (PMID 31552021, 2019). "In autoimmune Addison’s disease (AAD), candidate-gene and GWAS data converge on HLA-DR3/DR4 with replicated non-HLA signals (CTLA4, PTPN22, BACH2, SH2B3) and common AIRE effects, extending an “AIRE dosage” concept from rare monogenic APS-1 into common, complex autoimmunity." (PMID 41465179, 2025).